LEP (leptin)
Diseases named in the same sentence as LEP in open-access papers (continued):
Sharing a sentence is not in itself a finding about the gene and the disease.
tumor (continued). "However, the overexpression of leptin in obASCs and the impact it has on increasing the aggressiveness of tumor cell biology in vitro and in vivo has not been investigated." (PMID 26286584, 2015). "Expression levels of interleukin-13 (IL-13), leptin, lymphotoxin β receptor (LTbR), and macrophage inflammatory protein 1β (MTP1β) were significantly higher and expression level of IL-11Rα was lower for tumor-positive nodes as compared with tumor-negative SN." (PMID 24212647, 2011). "Moreover, increased leptin levels and availability to fatty acid (FA) also results in robust STAT3 signaling, which in turn promotes fatty acid β oxidation (FAO) and inhibits glycolysis due to glucose deprivation in TIME, leading to disability of CD8+ T cells to restrict tumor proliferation." (PMID 37266440, 2023). "These “conflicting” results might suggest that LEP hypermethylation-mediated leptin expression was an early event in MDS initiation but did not act as a tumor suppressor, and that they played a protective role during MDS progression, leading to favorable prognosis." (PMID 35847864, 2022). "In culture, leptin and IL-6 produced by obese adipocytes induced activation, proliferation, and migration of endothelial cells through upregulation of VEGF and VEGFR-2, suggesting that adipocytes secrete multiple factors that could enhance angiogenesis within the tumor microenvironment." (PMID 35435599, 2022). "Moreover, in triple-negative BC cell lines (MDA-MB-231, MDA-MB-468, and HCC-1806), a crosstalk between LEP and IGF-1 signaling has been demonstrated to promote the transactivation of the epidermal growth factor receptor (EGFR), which may enhance tumor cell invasion and migration." (PMID 36291602, 2022). "Likewise, IL-6 and leptin derived from adipocytes could increase the PD-L1/NKG2D ligand level in cancer cells by activating the JAK/STAT3 signaling pathway, thereby decreasing the cytotoxicity of NK cells to tumor cells." (PMID 33413697, 2021). "Moreover, our results also indicate a significantly positive correlation among leptin, IL-6, TNF-α and HGF and TNM stage, and a significantly negative correlation between adiponectin and TNM stage; suggesting that it should be considered as an important factor in tumor growth." (PMID 29088874, 2017). "However, leptin levels decreased during tumor progression in HFD mice (data not shown), suggesting that it may not be involved in the high tumor burden in the bone of HFD-exposed mice." (PMID 27049717, 2016). "Importantly, leptin induces the expression of inflammatory cytokines like IL-1 in tumor cells and non-tumor cells of the tumor stroma; however we were not able to demonstrate IL-1 upregulation by leptin in macrophages, although IL-1 is a major inducer of IL-6 in a variety of cells." (PMID 25599228, 2015). "However, tumors formed with a mixture of leptin shRNA obASCs and BCCs did not demonstrate similar reduction in IL-6, which suggests that other cells within the tumor microenvironment may be contributing to the increase in IL-6." (PMID 26286584, 2015). "In addition to confirming the presence of leptin, fatty acids and CCL2, we identified several other paracrine molecules produced by the crosstalk among the three cell types that also exhibit chemotactic, pro-angiogenic, pro-inflammatory, and tumor-promoting functions." (PMID 25599228, 2015). "Importantly, co-treatment with 3-MA, a pharmacological inhibitor of type III PI3K and finally inhibits autophagy, prevented leptin-induced tumor growth without significant effect by treatment with 3-MA alone, indicating a critical role of autophagic process in leptin-induced tumor growth." (PMID 25704884, 2015). "However, in these studies leptin’s impact on tumor angiogenesis was not investigated." (PMID 24202338, 2013). "Moreover, in these mice tumor VEGF was independent of host plasma leptin levels." (PMID 24202338, 2013).
tumor (continued). "Of note, tumor growth in the A-ZIP/F-1 mice, which are fatless and do not have detectable levels of leptin, was enhanced compared to wild-type mice." (PMID 33604295, 2020). "Neither secretion of adipocyte specific cytokines (leptin and adiponectin) nor angiogenesis factors (VEGF, HGF) or MCP1 and IL6 discriminate fat tissues from tumor-bearing (AdipTa or AdipTd) and tumor-free breasts (AdipN)." (PMID 32974182, 2020). "Compared to control HF group, LC and HC alone were not sufficient to reduce tumor growth in obese mice, despite the lower body weight and lower levels of IGF-1 and leptin in the HC group." (PMID 31906264, 2020). "Conversely, in tumour cells, MCF-7 and MDA-MB-231, leptin did not induce an efficient antioxidant response, at either concentration, resulting in an increase of lipid peroxidation products." (PMID 30563501, 2018). "The partial response to a leptin-blocking peptide is in agreement with Coward and colleagues’ finding that siltuximab treatment (an anti-IL6 antibody) significantly reduces tumor burden, but does not completely eliminate metastatic foci and ascites accumulation in xenograft mouse models." (PMID 26053184, 2015). "Also, in postmenopausal controls and cases there were positive correlation of leptin, resistin, and visfatin and negative correlations of adiponectin with TNM, tumor size, LN metastasis, and histological grade." (PMID 25838618, 2015). "The significant effect of this antibody on NO production despite of non-significant effects on tumor growth and EPC numbers may be because of use of large, pharmacological concentrations of leptin to demonstrate the 2 latter effects in this study." (PMID 21338489, 2011). "HIF1A-mediated LEP upregulation in an LKB1-depleted environment may augment the LUAD energetic burden via activation of downstream mitochondrial uncoupling players such as UCP2; however that regulation alone does not appear sufficient to confer lethality to LKB1 tumours." (PMID 39048991, 2024).
metabolic disorders (464 papers, 2005 to 2026). "In diabetic individuals, therefore, increased leptin expression in a positive feedback loop causes metabolic disorders." (PMID 41549047, 2026). "Leptin resistance, a hallmark of metabolic disorders, not only contributes to sustained inflammation, but also disrupts macrophage polarization, delaying fibrosis resolution." (PMID 40095902, 2025). "The reduced leptin levels in the SD-OP group, along with reduced aerobic performance, indicate an increased risk of metabolic disease and a reduced life expectancy." (PMID 40622971, 2025). "Dysregulation of leptin and insulin signaling has been linked to the development of metabolic disorders." (PMID 41040868, 2025). "When sleep deprivation occurs, leptin secretion decreases and hunger hormone (Ghrelin) secretion increases, causing metabolic disorders." (PMID 40655404, 2025). "Adiponectin and leptin, two prominent adipokines secreted by the adipose tissue, are associated with metabolic diseases yet present contrasting effects on such diseases." (PMID 38632706, 2024). "Its elevated concentration in ketotic cattle and associations with ghrelin and leptin further indicate IRSN’s potential as a biomarker for metabolic disorders, specifically subclinical ketosis, and its influence on glucose metabolism." (PMID 39109340, 2024). "The association of the adiponectin/leptin ratio with adipose tissue dysfunction and metabolic diseases were described, and current findings in COVID-19 disease encourage prospective studies to further evaluate this ratio as a clinical relevant indicator." (PMID 37238973, 2023). "A growing body of evidence also implicates ER stress in mediating the neurological damage and dysfunction caused by metabolic disease, including the associated weakening of hypothalamic leptin sensitivity." (PMID 36830084, 2023). "In this regard, a recent observational study linked a reduction of the adiponectin/leptin ratio, as found in patients with metabolic disease, to worse outcomes in COVID-1933." (PMID 36788324, 2023). "The db/db mouse is a genetically mutated mouse that is extremely obese having metabolic disorders with a defect in leptin function." (PMID 36985266, 2023). "Various metabolic disease-associated factors other than adiponectin have been reported to affect psoriatic skin phenotypes, such as leptin, chemerin, resistin, and free fatty acids." (PMID 37646025, 2023). "In the present study, adiponectin and leptin, the most essential adipokines associated with adiposity and metabolic disorders, were estimated among adolescents e with ID disabilities." (PMID 37730529, 2023). "Different studies and meta-analyses have shown that circulating leptin levels are associated with the severity of this metabolic disorder." (PMID 36674935, 2023). "Two adipokines involved in glucose and lipid metabolism, leptin and adiponectin, have been linked to early childhood growth regulation, energy balance, and metabolic disorders." (PMID 36120658, 2022). "Adipose tissue (AT) dysfunctions, such as adipocyte hypertrophy, macrophage infiltration and secretory adiposopathy (low plasma adiponectin/leptin, A/L, ratio), associate with metabolic disorders." (PMID 35436409, 2022). "PTP1B is well established in insulin signalling and leptin signalling and has been implicated in the dysfunction of these signalling pathways observed in metabolic disease." (PMID 35562959, 2022). "HFD usually induces elevated serum insulin and leptin levels, which are the indicators of insulin and leptin resistance, respectively, and risk factors for metabolic disorders." (PMID 36012616, 2022). "ET-1 signalling also has been linked to increased leptin production and stimulates the secretion of pro-inflammatory cytokines known to be involved in the development of metabolic disorders." (PMID 35681200, 2022).
metabolic disorders (continued). "The current study shows that disturbances in salivary leptin levels are linked to early childhood caries, a hormone whose importance has been recognized for several metabolic disorders." (PMID 36120658, 2022). "Microarray analysis has been performed in Lep KO rats to evaluate alterations in white adipose gene expression and to explore pathways involved in metabolic diseases with leptin deficiency." (PMID 33959146, 2021). "A growing body of evidence demonstrated that leptin changes are associated with metabolic disorders." (PMID 34407095, 2021). "Leptin is a critical hormonal regulator of metabolism, and leptin concentrations are directly associated with the subsequent development of metabolic disorders such as IR, T2D, and CVD." (PMID 34367173, 2021). "Metabolic disorders increase local and plasma active mediators or metabolites, including insulin, glucose, lipids, leptin, and adiponectin, reflecting early diagnostic abnormalities." (PMID 34737743, 2021). "In this group, the CRP and leptin levels were especially high indicating a different pathophysiological background, such as systemic inflammation or metabolic disorder, which we believe increases the cardiovascular risk." (PMID 32886313, 2021). "Leptin is a cytokine-like hormone with proinflammatory properties known to be associated with autoimmune disorders, infections, and endocrine and metabolic diseases." (PMID 32285743, 2020). "High concentrations of leptin are found in the serum of obese patients and are associated with an increased risk of cardiovascular and other metabolic diseases." (PMID 33138026, 2020). "Perinatal changes in leptin levels are associated with an increased risk of cardiovascular and metabolic diseases in adult life." (PMID 33396616, 2020). "Animal and human studies have demonstrated that prenatal PM2.5 exposure can induce sex-specific epigenetic modifications in leptin methylation, which is associated with adult metabolic disorders." (PMID 32102302, 2020). "In patients with genetic deficiency of leptin, exogenous leptin therapy effectively controls hyperphagia and corrects metabolic disorders." (PMID 31828124, 2019). "Our results suggest that metabolic disorders in normal weight children are associated with a high monosaccharide intake and elevated bacterial endotoxin as well as leptin plasma levels, the latter also discussed as being indicative of visceral adiposity." (PMID 30889844, 2019). "Overall, leptin gene deficiency led to metabolic disorders and inhibition of the AMPK signaling pathway in genetically obese mice." (PMID 31026583, 2019). "In menopausal women, there is a statistically significant positive correlation between the concentration of asprosin in the blood and the level of risk factors for metabolic disorders such as fasting glucose, atherogenesis index and leptin/adiponectin ratio." (PMID 31510055, 2019). "Age‐related obesity is characterized by leptin resistance and associated with heightened risk of metabolic disorders." (PMID 30821426, 2019). "Leptin deficiency changes gut microbiota in response to high-fat diet, while host genotypes show different responses to contribute to the development of metabolic disorder phenotypes, possibly linked with gut microbiota alteration." (PMID 31231354, 2019). "The adipokines leptin, adiponectin, resistin and visfatin are known mediators of inflammation and have all been implicated in metabolic diseases, including T2D." (PMID 29760587, 2018). "Our study also replicated well-known associations between leptin, adiponectin and metabolic disorders." (PMID 29759068, 2018). "For this, we chronically administered a BP3 expression vector to leptin deficient ob/ob mice, an animal model with metabolic disease and dysregulated lipogenic and gluconeogenic genes." (PMID 30374109, 2018).
metabolic disorders (continued). "In contrast to leptin, adiponectin levels are higher at birth than in childhood and adulthood and lower levels are associated with greater risk of metabolic disorders in adulthood." (PMID 25336252, 2014). "AACS is potentially being regulated by the leptin signaling pathway via the brain and consequently a cause of metabolic disorders." (PMID 25071839, 2014). "Few longitudinal and several cross-sectional studies examined the association between serum leptin and metabolic disorders." (PMID 24455217, 2013). "Data from cross-sectional studies suggest a gender disparity in the association between serum leptin levels and metabolic disorders." (PMID 24455217, 2013). "In the present study, we evaluated the effect of the Mukitake diet on the pathogenesis of metabolic disorders in leptin-deficient ob/ob mice." (PMID 23406154, 2013). "The metabolic and hepatic response to exogenous leptin treatment was associated with several factors, including the severity of metabolic disease at baseline, levels of triglycerides and triglyceride-rich apolipoproteins, baseline leptin levels, and changes in IGF-1 levels." (PMID 40520449, 2025). "Moreover, leptin and its receptor have been implicated in various other diseases beyond metabolic disorders." (PMID 40152811, 2025). "FKBP51 has been implicated in metabolic disorders through its modulation of the insulin receptor pathway and its correlation with leptin signaling, as well as by interacting with peroxisome proliferator-activated receptor-γ (PPARγ) and regulating the energy sensor AMPK." (PMID 39596380, 2024). "Likewise, leptin, a hormone involved in appetite regulation and energy balance and associated with a variety of metabolic diseases, and other pro-inflammatory cytokines such as IL-6 and TNF-α are essential in the pathophysiology of metabolic diseases." (PMID 39822427, 2024). "Gene Oncology (GO) Biological Process analysis was then performed and the results revealed DEGs were enriched in biological processes related to metabolic disease risk including “inflammatory response”, “lipid metabolism process”, and “cellular response to leptin stimulus”." (PMID 36709676, 2023). "However, we detected inverse relationships with MYOC expression with adipocyte size and serum leptin levels as parameters of AT dysfunction as well as with HOMA-IR indicating an association with early signs of metabolic disease." (PMID 36834493, 2023). "This review found that SGLT2i could cause weight loss through prompting lipid mobilization and lipolysis in DM patients and animals with metabolic diseases caused by high salt diet, high fat diet or leptin gene knockout." (PMID 38124893, 2023). "Overall, these data have shown that the key metabolites in intestinal microorganisms of ApoE-deficient and obese leptin-deficient mice with metabolic diseases may play causal roles in the pathophysiology of metabolic diseases." (PMID 36337626, 2022). "High leptin concentrations can cause more severe metabolic disorders which may lead to a reduction in muscle mass." (PMID 36675692, 2022). "Overall, these data have shown that the gut dominant microbiota have changed after knockout of ApoE-deficient and obese leptin-deficient, which may be closely associated with metabolic diseases." (PMID 36337626, 2022). "Leptin is another hormone that has been reported in HIV associated metabolic disorders." (PMID 34055923, 2021). "More studies are needed evaluating the levels of leptin in HIV associated metabolic disorders." (PMID 34055923, 2021). "Like leptin, galectin 3 is strictly associated with the development of metabolic disorders." (PMID 32859099, 2020). "Adiposity may increase the risk of metabolic disease, and in recent years adipokines and primarily leptin has been investigated." (PMID 30561133, 2019).